NFKB1 (nuclear factor kappa B subunit 1)
Diseases named in the same sentence as NFKB1 in open-access papers (continued):
Sharing a sentence is not in itself a finding about the gene and the disease.
breast carcinoma (continued). "Breast cancer tumorspheres presented a statistically significant increase in CXCL8, IL6, IL6R, and NFKB1 mRNA levels in comparison to adherent cell culture, while TGFB1 mRNA expression was decreased." (PMID 39336151, 2024). "To establish a link between miRNA, HIF-1α, and the COX-2/EP4/PI3K/Akt pathway, we measured NFκB1, COX-2, EP4, and VEGFA gene expression in breast cancer cell lines, in both normoxia and hypoxia." (PMID 32707933, 2020). "In this study, we analyzed the methylation status of the NFKB1 and the RELA gene in breast cancer, and found that the methylation level of the RELA gene was significantly correlated with the level of NF-κB1 transcripts under the influence of TNF-α." (PMID 31382678, 2019). "One study investigated common variants within the gene coding region for NF-kappaB and IkappaB, NFKB1 and NFKBIA, for involvement in sporadic breast cancer." (PMID 31874600, 2019). "We analyze the DNA methylation status of the NFKB1 gene and the RELA gene in breast cancer using pyrosequencing." (PMID 31382678, 2019). "In summary, our study suggests that the crosstalk between NFATc2, NFKB1/RELA, and CRE region regulates Ets1 gene transcription in metastatic breast cancer cells." (PMID 30467308, 2018). "Compared with the less metastatic breast cancer cells, metastatic breast cancer cells (MDA-MB-231) show open chromatin configurations in the CRE, which facilitates direct binding of NFATc2 and/or NFKB1/RELA complex to trans-activate Ets1 transcription." (PMID 30467308, 2018). "The results suggest that signaling proteins affected by EGCG in breast cancer, which include JUN, FADD, NFKB1, Bcl-2, GNAO1, and MMP14, are involved primarily in cell death and survival; DNA replication, recombination and repair; and the cell cycle." (PMID 28713815, 2017). "Several nodes in this pathway emerged as potential direct targets of EGCG in breast cancer: JUN, FADD, NFKB1, Bcl-2, GNAO1, and MMP14." (PMID 28713815, 2017). "In particular, we identified JUN, FADD, NFKB1, Bcl-2, GNAO1, and MMP14 as potential targets of EGCG in breast cancer." (PMID 28713815, 2017). "The signature profile analysis of CXCL8, IL6, and NFKB1 revealed a higher mRNA expression in non-responder breast cancer patients (p = 0.015)." (PMID 39336151, 2024). "CXCL8 (p = 0.12), IL6 (p = 0.022), and NFKB1 (p = 0.0097) mRNA levels were higher in breast cancer patients who did not respond to chemotherapy treatment." (PMID 39336151, 2024). "In A549 lung cancer cells, MDA-MB-231 breast cancer cells, and HepG2 liver cancer cells, ibuprofen inhibited inflammation-related stemness genes, including IL-1α, IL-1β, ICAM3, CCL16, TRAF6, PDE3A, PRTN3, NFκB1, IκBκB, and BCAR1." (PMID 35267528, 2022). "Moreover, we tested the expressions of NFKB1, RAC1and BRD4 in different molecular subtypes of breast cancer cells followed by NSC/JQ1 combined treatment." (PMID 34803511, 2021). "Moreover, ICAM3, CCL16, PDE3A, PRTN3, TRAF6, BCAR1, IL-1α, IL-1β, NFκB1, SOX2 and OCT4 decreases the protein expression as indicated by immunofluorescence staining in the ibuprofen-treated MDA-MB-231 breast cancer cells versus the control." (PMID 32528119, 2020).
breast carcinoma (continued). "Compared with less metastatic cells (MCF-7), metastatic breast cancer cells (MDA-MB-231) have relatively open chromatin structure on the CRE, which facilitates direct binding of NFATc2 and NFKB1/RELA to enhance Ets1 expression and invasiveness of metastatic breast cancers, accordingly." (PMID 30467308, 2018). "Our network analysis also allowed us to identify several specific proteins that EGCG may help regulate in breast cancer, including JUN, FADD, NFKB1, Bcl-2, GNAO1, and MMP14." (PMID 28713815, 2017). "In addition, we observed feedback loops concerning nuclear factor kappa B subunit 1 (NFKB1) activation (CHUK, NFKBIA; related to cell survival) in bladder cancer, anti-apoptotic BIRC2/3, and pro-apoptotic TRAF1 factors in breast cancer, respectively." (PMID 28775339, 2017). "Also in MCF-7 breast cancer cells RELA and NFKB1 triggered CCID formation." (PMID 26513020, 2015). "In summary, the obtained results showed that D-glucuronyl C5-epimerase significantly suppress proliferative activity of breast cancer cells in vitro through the activation of tumour suppressor genes р53, BRCA1, SYK and E2F1 and change of a balance of pro- and apoptotic factors BCL2, NFKB1 and TNF." (PMID 20723247, 2010). "The obtained data indicated that antimitotic effect of D-glucuronyl C5-epimerase in human breast cancer cells in vitro probably is realized mainly via the activation of tumour suppressor genes р53, BRCA1, SYK and E2F1 and change of a balance of pro- and anti-apoptotic factors BCL2, NFKB1 and TNF." (PMID 20723247, 2010).
colitis (1,479 papers, 2005 to 2026). Inflammation of the colon. "By the end of the experimental procedure, all mice in the wild‐type, Nfkb1−/−, and c‐Rel−/− groups had developed clinical colitis with weight loss and diarrhoea; several mice also developed haematochezia." (PMID 25727407, 2015). "Two patients had pathogenic variants in NFKB1, of whom one had a coeliac-like inflammation in the small bowel but was additionally infected with norovirus (# 18); the other patient had an acute duodenitis and ileitis, as well as signs of colitis." (PMID 34599484, 2022). "To address this, we have studied the effects of DSS/AOM‐induced colitis‐associated carcinogenesis in mice carrying germline deletions of the Nfkb1, Nfkb2 or c‐Rel genes and have also investigated the impact of these deletions on DSS‐induced colitis and colonic responses to DNA damage." (PMID 25727407, 2015). "Thus Nfkb1 is an inhibitor of key immunoregulatory genes, and this is manifest in the observation that Nfkb1−/− mice are highly susceptible to microflora-induced colitis." (PMID 22427889, 2012). "Intestinal dysfunctions, particularly those involving TLRs, IFNG, NFKB1, and TNF, have established pathogenic roles in several mouse models of colitis and in the onset of human IBD." (PMID 35732858, 2022). "To investigate the effect of NF‐κB subunit loss on colitis‐associated carcinogenesis, we administered azoxymethane followed by pulsed dextran sodium sulphate to C57BL/6, Nfkb1−/−, Nfkb2−/−, and c‐Rel−/−mice." (PMID 25727407, 2015). "CD4-neighbouring SIGLEC8 RNA molecules were also significantly associated with NF-κB (NFKB1) and IFNγ (IFNGR1, STAT1 and IRF1) signalling components, which indicates that the same pathways might drive interactions between A-Eos and CD4+ T cells in mouse and human colitis." (PMID 36509106, 2023). "When transgenic mice lacking specific NF-κB subunits were subjected to dextran sulphate sodium (DSS) treatment in a model of colitis, mice lacking cRel and Nfkb1 developed more severe colitis than wild-type controls, whereas Nfkb2−/− mice were resistant to colitis." (PMID 32958515, 2020).
Sepsis (1,182 papers, 2003 to 2026). Sepsis is defined as life-threatening organ dysfunction caused by a dysregulated host response to infection. "Other transcripts upregulated in CD5L− peritoneal cells, including Osm, Il18bp, Ripk1, Nub1, Tlr2, Stat1, Irf1, Nfkb1, Pik3r5, or their coding proteins, were already associated with sepsis severity." (PMID 38750020, 2024). "NFKB1 overexpression was associated late-onset sepsis (p = 0.002), cohorts with hemodynamic instability (p = 0.044), poor feeding (p = 0.032), and oliguria (p = 0.026)." (PMID 34183713, 2021). "We have already shown that the D allele of the functional NFKB1 insertion/deletion (−94ins/delATTG) (rs28362491) polymorphism is associated with increased 30-day mortality in patients with severe sepsis." (PMID 27249028, 2016). "To date, Adamzik and Schafer have reported that the deletion allele of the NFKB1 insertion/deletion (−94 ins/delATTG) polymorphism is associated with increased 30-day mortality in patients with severe sepsis and septic shock." (PMID 25880845, 2015). "As we have recently shown, the -94 Ins/Del NFKB1 promoter polymorphism influences sepsis mortality." (PMID 27249028, 2016). "Integrating NFκB1 with its regulatory targets provides a comprehensive framework to understand the multifaceted pathophysiology of sepsis, including immunological dysregulation, oxidative stress, metabolic imbalance, and tissue remodeling." (PMID 41303672, 2025). "In particular, its increased expression during sepsis contributes to the suppression of macrophage migration, as well as a decrease in NFKB1 transcriptional activity and the downstream cytokines TNF-α and IL-6." (PMID 36670868, 2022). "ROC analysis revealed circulatory levels of MYD88 and NFKB1 transcripts to be good biomarkers for sepsis in neonates." (PMID 34183713, 2021). "We then selected four SNPs (NFKB1 rs28362491 ins/delATTG, rs4648068 A/G, RELA rs7119750 C/T, and REL rs842647 G/A) from the canonical pathway of NF-κB and investigated their clinical relevance in relation to the development of sepsis and MODS." (PMID 25880845, 2015). "SNPS in NFKB1 loci rs41275743 and RS4648143 are associated with the risk of AKI in sepsis patients." (PMID 35874763, 2022). "ROC analysis revealed MYD88 and NFKB1 transcripts to be good biomarkers for sepsis." (PMID 34183713, 2021). "In light of the present findings, the development and validation of new approaches for neonatal sepsis treatment are recommended, such as the potential use of TLR-pathway antagonists/inhibitors to limit the TLRs association with MyD88 preferentially and reduces the NFKB1 activity and/or IL68,39–41." (PMID 34183713, 2021). "Thus, promoter activity might be varying depending on the NFKB1 genotype, explaining the genotype dependent mortality from sepsis, and one likely mechanism is the degree of promoter methylation." (PMID 27249028, 2016). "Across all neonates, relative expression levels of MYD88 (p < 0.001), NFKB1 (p < 0.001), and IL6 (p = 0.027) were significantly higher in sepsis cases compared to controls." (PMID 34183713, 2021). "Gene co-expression analysis across the 124 sepsis cohorts showed that IL6 gene expression was directly correlated to MYD88 (r = 0.26, p = 0.004) and NFKB1 (r = 0.19, p = 0.039) transcript levels." (PMID 34183713, 2021). "NFκB1 and KLF6 synergistically amplify the inflammatory response in sepsis." (PMID 41303672, 2025). "AopP hinders the NF-κB signaling pathway by restraining the transportation of the p50/p65 protein complex (NFKB1/RelA) into the target cell’s nucleus, resulting in the septicemia and furuncles formation (subcutaneous wounds) in host tissue." (PMID 36363710, 2022).
Sepsis (continued). "In our study, whole lung levels of nuclear factor kappa B (NFkb1) and toll-like receptor 4 (Tlr4) were not significantly altered by Rabeprazole treatment in basal or sepsis-challenged mice." (PMID 35563731, 2022). "MYD88, NFKB1, and IL6 relative expressions were significantly higher in sepsis cases than controls." (PMID 34183713, 2021). "From the perspective of the centrality of the PPI network, this result suggests that most of the interacting and bottleneck genes like NFKB1, SRC and MYC could have important roles in the pathogenesis of sepsis." (PMID 30297806, 2018). "In sepsis, RELA, CEBPB, NFKBIA, STAT6, IRF8 and SPI1 were downregulated, with no significant change in NFKB1, JUN and GLI1." (PMID 39444551, 2024).
atherosclerosis (1,159 papers, 2006 to 2026). A disease characterized by the build-up of fatty material and calcium deposition in the arterial wall resulting in partial or complete occlusion of the arterial lumen. "In parallel we observed reductions in circulating monocytes and aortic arch Rela/Nfkb1, genes that transcribe NF-κB – both potential mechanisms to explain the reduction in atherosclerosis." (PMID 40893367, 2025). "NFKB1 is the most highly expressed transcription factor in macrophages and is essential to the mechanisms of atherosclerosis development." (PMID 37741880, 2023). "For example, we recently showed that atherosclerosis-prone aortic regions such as the aortic arch had lower levels of homeobox genes and higher levels of nuclear factor kappa-B (Nfkb1) activity than the atherosclerosis-resistant descending thoracic aorta." (PMID 24442477, 2014). "Notably, ERK (Mapk1, Mapk3), IKBKB (Ikbkb), and NF-κB (Nfkb1) were included in Lipid and atherosclerosis." (PMID 40438398, 2025). "Comparison of top-scored IPA canonical analysis showed that atherosclerosis signaling may relate to interactions between CLU and proteins encoded by congenital toxoplasmosis susceptibility genes (TGFβ1, COL2A1, ALOX12, NFκB1)." (PMID 28904337, 2017). "Moreover, our study constructed miRNA-mRNA and TF-mRNA regulatory networks, finding that regulators such as hsa-miR-203a-3p, RELA, and NFKB1 play core roles in this network, further supporting the complex molecular interactions between gout and atherosclerosis." (PMID 39677038, 2024). "In rat atherosclerosis PCR array, Abca1, Bax, Bcl2, Bcl2a1, Cd44, Fabp3, Hbegf, Lypla1, Ptgs1, Selplg, Tgfb2, Tnc, and Vegfa had reverse trend between WT and MU groups, while the trends of Bcl2l1, Bid, Birc3, Cxcl1, Fas, Fn1, Itga2, Itga5, Lif, Nfkb1, Nr1h3, Ppard, and Sod1 were consistent." (PMID 34545275, 2021). "SIN mainly affected 5 target genes, NFκB-1, TNF, interleukin 6, interleukin 1β and signal transducer and activator of transcription 3, and IL-17, AGE-RAGE signaling pathways, lipids, and atherosclerosis were all controlled to achieve therapeutic effects." (PMID 38206710, 2023).
diabetes (1,028 papers, 2006 to 2026). "The polymorphism of the NFKB1 gene is related to diabetes and its complications, especially the development of DN55." (PMID 40461634, 2025). "NFKB1 encodes a subunit of NF-kappa B. It is specifically involved in anti-inflammatory effects, and that inflammation is linked to insulin resistance and diabetes." (PMID 32143602, 2020). "The top contributing features identified for the combined model through RFECV included three molecular markers—miR342, NFKB1, and miR636—and two biochemical markers the albumin-to-creatinine ratio and HDLc, indicating their strong association with diabetes progression." (PMID 40533788, 2025). "The feature importance for the combined model identified the 5 most contributing features for predicting diabetes stages, comprising three molecular markers—miR342, NFKB1, and miR636—and two biochemical markers, the albumin-to-creatinine ratio and HDLc." (PMID 40533788, 2025). "Compared with the normal control group, the mRNA levels of NLRP3, NFE2L2, and NFKB1 in the diabetes model group were significantly increased, while they decreased in the SAL treatment group (P < 0.05), with the statistical difference." (PMID 38243268, 2024). "NFKB1 variations contribute to the development of type 2 diabetes mellitus, and the expression of NFκB is upregulated in diabetic patients." (PMID 36094934, 2022). "Similar to NOD/ShiL.tj mice, 90% of female mice and 52% of male mice acquired diabetes at 30 weeks of age in the F15 NOD Nfκb1 wild-type mice." (PMID 35740465, 2022). "Results indicated several independent risk factors for CAD development, including del/del genotype of NFKB1 -94 ATTG ins/del polymorphism, TC, HDL-C, LDL-C, smoking, diabetes and hypertension." (PMID 29911119, 2018). "Mapk1, Mapk3, Ikbkb, and Nfkb1 were expressed at higher levels in the diabetic liver injury group." (PMID 40438398, 2025). "Additionally, diabetes increased the nuclear factor kappa B subunit 1 protein (p50) expression, a repressor of Slc2a4, which was also predicted as a target for miR-199a-5p and miR-532-3p." (PMID 30258406, 2018). "The previously identified UMOD locus showed genome-wide significant association with eGFRcrea among those with diabetes (rs12917707, P value=2.5 × 10−8), and six loci (NFKB1, UNCX, TSPAN9, AP5B1, SIPA1L3 and PTPRO) had nominally significant associations with eGFRcrea among those with diabetes." (PMID 26831199, 2016). "Furthermore, the pathways related to cancer and HIF-1 signaling, although having less direct connection with diabetes, may exert anti-inflammatory or antioxidant effects through common targets such as NFKB1." (PMID 40508108, 2025). "For hsa-miR-548k, main targets involved in diabetes-related pathways were identified, including TGFBR1, STAT1, NFKB1, MAPK1, and STAT5A." (PMID 40788916, 2025). "The main molecular pathways involved in our study, namely CXCR, NOTCH, STAT, NFKB1 and FGFR pathways, have a well-documented role in diabetes and CAD." (PMID 39974596, 2025). "The main molecular pathways involved were CXCR, NOTCH, STAT, NFKB1 and FGFR pathways, which have a well-documented role in diabetes and CAD." (PMID 39974596, 2025). "Among the common genes of depression and diabetes, there are four TFs, namely, BCL3, MXI1, GMEB2, NFKB1." (PMID 34833079, 2021). "In the multiple binary logistic regression analysis, diabetes, hypertension, smoking, LDL-cholesterol, total cholesterol, HDL-cholesterol and NFKB1 -94ATTG del/del genotype were identified as significant and independent risk factors for CAD development." (PMID 29911119, 2018). "Also, mTOR, nuclear factor NF-kappa-B (NFKB1) and RB1-inducible coiled-coil 1 (RB1CC1) are autophagy-related genes that affect diabetes pathogenesis." (PMID 40533788, 2025). "In order to verify whether ESR1, EP300, NFKB1, and HDAC1 are relevant in ginsenoside treatment of diabetes, Western blot analysis was performed on pancreatic tissue from STZ-induced T1DM mice treated with AD-1." (PMID 40508108, 2025).
diabetes (continued). "In the present study, we investigated the following risk factors of MACCEs, including the age, sex, hypertension, diabetes, total cholesterol level, triglyceride level, and LDL-C level, as well as the NFKB1 gene with a difference in genotype distribution between the MACCE and non-MACCE groups." (PMID 35831800, 2022). "In addition, the inhibition of the NFKB1 and NFKB2 genes shows a decrease in the inflammatory process, consequently improving hypertension and suppressing vasoconstriction induced by diabetes." (PMID 34366888, 2021). "Moreover, we verified the therapeutic effect of the ginsenoside derivative AD-1 in STZ-induced T1DM mice and observed downregulation of key target proteins (e.g., NFKB1 and HDAC1) in the mouse pancreas, thus providing a basis for innovative applications of ginsenosides in the treatment of diabetes." (PMID 40508108, 2025).